LCN2 (lipocalin 2)
Diseases named in the same sentence as LCN2 in open-access papers (continued):
Sharing a sentence is not in itself a finding about the gene and the disease.
Gestational Diabetes Mellitus (6 papers, 2016 to 2024). "One-way logistic regression analysis revealed a significant increase in the risk of gestational diabetes mellitus (GDM) with a rise in chemerin concentration by 10 ng, LCN2 by 1 ng, and apelin by 1 ng (1000 pg)." (PMID 38203346, 2023). "It is suggested that LCN2 could play a role in pathogenesis of gestational diabetes through influence on inflammation and endothelial cell dysfunction." (PMID 38203346, 2023). "Furthermore, meta-analysis of data comparing gestational diabetes mellitus (GDM) patients to parturient with normal glucose tolerance identified higher blood LCN2 in GDM patients." (PMID 38645429, 2024). "The aim of this study is to determine serum adiponectin, chemerin, lipocalin 2 and apelin levels in GDM patients, assess the correlation between these adipokines and discuss their possible role in the diagnosis and pathogenesis of gestational diabetes mellitus." (PMID 38203346, 2023).
hyperuricemia (6 papers, 2020 to 2026). An abnormally high level of uric acid. "Meanwhile, 3-MA showed a protective effect against tubular damage as indicated by reduction of Lcn2 and KIM-1 expressions in the hyperuricemia group." (PMID 32555189, 2020).
IgA nephropathy (6 papers, 2015 to 2024). "The leakage of HAVCR1 and LCN2 into urine could be detected in IgA nephropathy." (PMID 26317775, 2015).
left ventricular hypertrophy (6 papers, 2018 to 2026). Enlargement of the LEFT VENTRICLE of the heart. "Furthermore, as LCN2 levels are positively correlated with left ventricular hypertrophy, longitudinal measurements of LCN2 and cardiac size in long-term athletes may yield interesting results as exercise induces physiological hypertrophy of the heart." (PMID 33603000, 2021).
psoriasis vulgaris (6 papers, 2015 to 2025). Plaque psoriasis is the most common presentation of psoriasis. "We found that both Tcf7l1 and LCN2 were highly expressed in those diseases characterized by defective keratinocyte differentiation (especially psoriasis vulgaris, condyloma acuminatum, squamous cell carcinoma, etc)." (PMID 27551519, 2016). "Serum lipocalin-2 (LCN-2) levels are associated with the visual analogue scale score of itch in patients with psoriasis vulgaris (PSO), but not other itchy skin diseases." (PMID 40666493, 2025). "For example, while LCN2, WNT5A, and KRT6 (cluster 1) are all highly up-regulated in psoriasis vulgaris LS, these genes, which show constitutively high expression in scalp NL and N biopsies, are up-regulated to a lesser degree in LS scalp biopsies." (PMID 26849645, 2016). "The increased in expression of b-defensin-4 and lipocalin-2 combined with the hyperproliferative phenotype of acral skin indicate that from morphological and functional point of view, the skin of palms and soles is intermediate between normal non-acral skin and psoriasis vulgaris." (PMID 27152848, 2016).
pulmonary fibrosis (6 papers, 2022 to 2026). Chronic progressive interstitial lung disorder characterized by the replacement of the lung tissue by connective tissue, leading to progressive dyspnea, respiratory failure, or right heart failure. "Our integrative analysis reveals novel molecular connections between cellular senescence programs and fibrotic lung remodeling, positioning CLU and LCN2 as pivotal regulators of age-associated pulmonary fibrosis." (PMID 41562054, 2025). "The development of BLM-induced pulmonary fibrosis and the impairment of respiratory functions were associated with increased lung tissue Lcn2 mRNA expression, as detected with Q-RT-PCR, in all phases of the disease, but especially in the acute inflammatory phase." (PMID 37746070, 2023). "Lipocalin-2 (LCN2) is a secretory glycoprotein upregulated by oxidative stress; moreover, patients with idiopathic pulmonary fibrosis (IPF) have shown increased LCN2 levels in bronchoalveolar lavage fluid (BALF)." (PMID 38704585, 2024). "Here, we first used a BLM-treated mouse model to characterize the expression of LCN2 in the lung fibrosis region and analyzed the location of LCN2 in alveolar epithelial cells." (PMID 39139502, 2024). "We used a BLM-treated mouse model to characterize the expression of LCN2 in lung fibrosis regions and analyzed the location of LCN2 in alveolar epithelial cells." (PMID 39139502, 2024). "Similar results were obtained in BLM-induced pulmonary fibrosis in mice, further indicating higher Lcn2 expression in the acute phase of the disease, following BLM-induced epithelial damage and correlating with neutrophilic inflammation." (PMID 37746070, 2023). "NGAL, also known as lipocalin 2 (LCN2), is significantly increased in BALF of mice with bleomycin‐induced pulmonary fibrosis and in human IPF patients." (PMID 41496587, 2026). "To examine Lcn2 expression in the lungs of mice post-bleomycin (BLM)-induced pulmonary inflammation and fibrosis, a widely used animal model of pulmonary fibrosis, we mined the relative transcriptomic datasets from Fibromine, as in IPF patients." (PMID 37746070, 2023). "We hypothesize that through targeted modulation of LCN2 and CLU, these agents may attenuate pulmonary fibrosis progression, suggesting a novel therapeutic strategy for IPF." (PMID 41562054, 2025). "LCN2 and MMP-9 have been reported to participate in pulmonary fibrosis development." (PMID 34991559, 2022).
Salmonella Infections (6 papers, 2009 to 2022). Infections with bacteria of the genus SALMONELLA. "It is conceivable that the survival of mice in the late stages of systemic Salmonella infection is directly or indirectly influenced by the intestinal microbiome, which is modulated by Lcn2." (PMID 28443246, 2017). "Splenic Lcn2 receptor (LcnR) expression was significantly reduced following Salmonella infection, and Lcn2 mRNA expression in the spleen was higher in Hfe−/− as compared to congenic WT mice." (PMID 28443246, 2017). "Importantly, nifedipine significantly increased LCN2 expression upon Salmonella infection as compared to macrophages treated with Salmonella alone." (PMID 35743233, 2022). "However, Salmonella infection induces Lcn2 production in the intestine, and the ability to utilize Gly-Ent confers a competitive advantage over an iroN mutant during intestinal inflammation." (PMID 19834550, 2009). "This is linked to host control of Salmonella infection, as we could demonstrate herein that DMT1 induction by nifedipine increases LCN2 expression and that nifedipine-mediated LCN2 induction in RAW267.4 macrophages reduces intramacrophage Salmonella multiplication." (PMID 35743233, 2022). "Altogether, these data suggest that high levels of Lcn2 expression in a context of low Hamp expression do not protect Ank1Ity16/Ity16 mutant mice from systemic Salmonella infection." (PMID 23390527, 2013).
sarcopenia (6 papers, 2021 to 2026). Progressive decline in muscle mass due to aging which results in decreased functional capacity of muscles. "LCN2, an inflammation-related factor with elevated expression in the skeletal muscle of ob/ob mice with sarcopenia, is associated with muscle atrophy-related inflammation and oxidative stress." (PMID 36313746, 2022). "The aim of the present study was to clarify the role of LCN2 in inflammation, oxidative stress, and iron accumulation in relation to muscle atrophy, which has been associated with the acceleration of sarcopenia." (PMID 34064680, 2021). "Obese sarcopenia is associated with a dysregulation of muscle iron metabolism, which could be further investigated by examining LCN2/24p3R signaling-mediated muscle atrophy." (PMID 34064680, 2021). "In particular, LCN2/24p3R-mediated iron uptake may cause iron accumulation, oxidative stress, and inflammation, ultimately resulting in obese sarcopenia." (PMID 34064680, 2021). "Lipocalin-2 (LCN2) is an iron-binding protein that has been associated with skeletal muscle regeneration, but details regarding its role in obese sarcopenia remain unclear." (PMID 34064680, 2021). "The increase in LCN2-related iron uptake in obese sarcopenia in the present study was similar to that observed in the heart of ob/ob mice." (PMID 34064680, 2021). "We demonstrate here for the first time that LCN2/24p3R-mediated iron accumulation is upregulated in obese mice with sarcopenia." (PMID 34064680, 2021). "RNA sequencing analyses indicated the LCN2 gene expression is enhanced in skeletal muscle of ob/ob mice with sarcopenia." (PMID 34064680, 2021). "In this regard, we hypothesize that LCN2, as a proinflammatory adipokine, plays a critical role in inflammation and iron dysregulation-mediated oxidative stress in ob/ob mice with sarcopenia." (PMID 34064680, 2021). "However, the potential role of LCN2 in regulating iron homeostasis and oxidative stress in obese sarcopenia remains poorly understood." (PMID 34064680, 2021). "Integrating mouse and human liver transcriptomics with muscle proteomics from MCD- and GAN-diet induced murine MASH models with sarcopenia, we identified three MASH-induced hepatokines, namely LCN2, LGALS3 and OPN." (PMID 42270040, 2026).
schizophrenia (6 papers, 2012 to 2021). A major psychotic disorder characterized by abnormalities in the perception or expression of reality. "We sought to assess the role of Lcn2 in mediating excess glial cells and schizophrenia-related behavior by crossing mice that lack both alleles of Lcn2 to either WT mice or Disc1-L100P mutants." (PMID 23272119, 2012). "Here, we describe for the first time, an association of schizophrenia-related behavior in Disc1 mutant mice with increased LCN2 and GFAP+ glial cells in the SVZ." (PMID 23272119, 2012). "Our work demonstrates that pharmacological intervention can prevent the onset of schizophrenia-related behaviors and suggests Lcn2 as a novel drug target for preventive treatment of schizophrenia." (PMID 23272119, 2012). "Lcn2 is a potential novel drug target for early intervention in schizophrenia." (PMID 23272119, 2012). "LCN2 might also be useful as new biomarker for the prodromal stage of schizophrenia and as a potential new therapeutic target." (PMID 23272119, 2012). "Interestingly, the remaining genes in which immobilization (Immo+FC) had induced changes in expression seem to be involved in immune response (Lbp and Lnc2), anxiety behavior and schizophrenia (Pde7b), corticosterone homeostasis, and steroid transportation (Lcn2 and Soat1)." (PMID 30705647, 2018). "Finally, we assessed effect of genetic inactivation of Lcn2 on schizophrenia-related behaviors." (PMID 23272119, 2012). "We have identified a novel function for Lcn2 as a regulator of glial proliferation in the SVZ and of behaviors relevant to schizophrenia." (PMID 23272119, 2012).
age-related macular degeneration (5 papers, 2020 to 2024). Age-related loss of vision in the central portion of the retina (macula), secondary to retinal degeneration. "NF-κb can regulate the upregulation of LCN2 expression and stimulate inflammatory response in age-related macular degeneration (AMD)–induced inflammation." (PMID 34616693, 2021). "STAT1 and NF-κB may work together as a complex to control the upregulation in LCN2 expression in the retina and stimulate an inflammatory response, leading to increased infiltration of LCN2-positive neutrophils in the choroid and retina of early age-related macular degeneration." (PMID 36555403, 2022).
alcoholic steatohepatitis (5 papers, 2016 to 2023). "Likewise, mice treated with ethanol exhibited elevated LCN2 expression in neutrophils, and Lcn2-deficient mice are protected from alcoholic steatohepatitis (ASH) as demonstrated by reduced neutrophil infiltration and liver injury." (PMID 34675931, 2021).
anaplastic thyroid carcinoma (5 papers, 2010 to 2022). "In the thyroid, IHC analysis of different thyroid tissues showed that tissues derived from papillary, follicular, and anaplastic thyroid carcinomas had significantly higher levels of LCN2 expression compared to normal thyroid tissue." (PMID 32575507, 2020). "In fact, the study showed that increased LCN2 levels were proportional to the malignant phenotype of these tumors, the anaplastic thyroid carcinoma being the one with the highest LCN2 expression." (PMID 32575507, 2020).
ankylosis (5 papers, 2020 to 2024). Fixation and immobility of a joint. "Recently, using ank/ank mice with a fused spine, we identified the LCN2-associated pathway and showed that higher LCN2 levels correlate with more severe ankylosis in AS patients." (PMID 35804445, 2022). "In ankylosing spondylitis, elevated lipocalin-2 values were found, and in the ank/ank mutant mice, a mouse model for ankylosing spondylitis, increased lipocalin-2 levels were associated with the coexistence of ankylosis and gut inflammation observed in these animals." (PMID 33499006, 2021). "In summary, the dysregulation of lipocalin 2 associated with coexisting gut inflammation and ankylosis in the ank/ank mouse model and human patients indicates a novel mechanism for inflammation and ankylosis of gut-joint coexistence." (PMID 32188494, 2020). "The association of lipocalin 2 with concurrent inflammation and ankylosis in the ank/ank mice and human patients indicates that lipocalin 2 could be a potential pathway involved in AS and IBD." (PMID 32188494, 2020). "In this study, we aimed to decipher whether lipocalin 2 and its association with PPARγ mediate the gut-joint axis, by using the ank/ank mutant mouse model with concurrent progressive ankylosis and subclinical gut inflammation." (PMID 32188494, 2020). "In summary, lipocalin 2 modulated by PPARγ could be a potential pathway involved in concurrent inflammation and ankylosis in AS and IBD." (PMID 32188494, 2020). "As elevated LCN2 levels implicate ongoing gut inflammation and progressive spinal ankylosis, our findings suggest that normalization of LCN2 through modulation of PPARγ could be viewed as a treatment target in AS and IBD." (PMID 32188494, 2020). "Moreover, in patients with less severe ankylosis, higher LCN2 levels are detected in those with coexistent IBD (220 ± 11 ng/ml; p < 0.01), confirming the contribution of gut inflammation in the elevation of LCN2." (PMID 32188494, 2020).
atopic dermatitis (5 papers, 2014 to 2026). "In addition, LCN2 derived from spinal astrocytes has been found to enhance itch in a mouse model of atopic dermatitis (AD)." (PMID 30805373, 2019).
bladder infection (5 papers, 2014 to 2022). "Among hormones, insulin has the ability to promote the secretion of RNase 7, RNase4, and LCN2, which are proven to be against bladder infection caused by a variety of uropathogens." (PMID 36081496, 2022). "Nevertheless, further studies are imperative to explore the specific mechanism by which the LCN2, TLR-4, and JAK/STAT pathways participate in UPEC-induced inflammation, with the goal of developing more effective therapies for cystitis." (PMID 36555403, 2022). "Further studies should explore specific mechanisms by which the LCN2, TLR-4, and JAK/STAT pathways participate in UPEC-induced inflammation to facilitate the development of effective therapies for cystitis." (PMID 36555403, 2022).
cerebrovascular diseases (5 papers, 2020 to 2023). "We investigated the association of white matter changes and LCN2 in patients with cerebrovascular disease (SVDND, VCIND, and VaD) in cohorts 1 and 4 excluding patients with radiological evidence for cortical infarctions." (PMID 32001681, 2020). "Lcn2 expression is often upregulated in cerebrovascular diseases, and deletion of LCN2 has frequently been shown to protect against infiltration of inflammatory mediators." (PMID 37884959, 2023). "The expression of LCN2 can be highly upregulated in cerebrovascular diseases, and Lcn2 deletion has frequently been shown to provide protection against inflammatory infiltration and inflammatory mediator production." (PMID 35241660, 2022).
chronic myeloid leukemia (5 papers, 2014 to 2025). "LCN2 mRNA expression was 20-fold upregulated in peripheral blood (PB) mononuclear cells of chronic myeloid leukemia (CML) and myelofibrosis (MF) patients vs. healthy controls." (PMID 34439364, 2021). "Due to the fact that the oncogenic tyrosin kinase BCR-ABL (for breakpoint cluster region-Abelson) represses LCNR expression, iron-deprivation via the LCN2-LCNR pathway is inactive in BCR-ABL+ CML (chronic myeloid leukemia) cells, rendering them resistant to apoptosis." (PMID 30534534, 2018). "Although the differences in the two forms of LCN2 were not the result of glycosylation in the case of chronic myelogenous leukemia, our results suggest that multiple glycoforms of urinary LCN2 can be generated by changing the attached N-glycans." (PMID 26949374, 2016).
disc degeneration (5 papers, 2019 to 2025). "In vivo, AAV9‐mediated FBXO2 delivery attenuated disc degeneration in rats by suppressing ferroptosis and restoring collagen II expression, whereas FBXO2 KO accelerated IVDD via LCN2‐dependent pathways." (PMID 40791152, 2025). "Complementary in vivo studies demonstrate that FBXO2 overexpression attenuates disc degeneration in rodent IVDD models, whereas FBXO2 deletion exacerbates disease progression through LCN2‐mediated ferroptotic pathways." (PMID 40791152, 2025). "However, the role of LCN2 to disc degeneration remains largely unknown." (PMID 31027158, 2019). "Functional validation identified LCN2 as a critical immunomodulator, rescuing inflammatory imbalance via regulating ANXA1/Arginase‐1 expression, thus highlighting its therapeutic potential in degenerative disc disease." (PMID 40570207, 2025).
endometriosis (5 papers, 2017 to 2025). The growth of functional endometrial tissue in anatomic sites outside the uterine body. "More studies are essential to clarify how LCN2 is related to the initiation and progression of endometriosis." (PMID 38645429, 2024). "In endometriosis patients, there was not only a systemic increase in LCN2, but also locally in endometrial cysts, as demonstrated by immunohistochemical staining." (PMID 38645429, 2024). "A study in mice that dealt with the molecular interactions that LCN2 plays in endometriosis found that LCN2 expression induces epithelial-to-mesenchymal transition (EMT) in stressed primary uterine endometrial cells promoting onset of endometriosis." (PMID 38645429, 2024). "Since endometriosis patients have an almost three times higher incidence of developing cancer, it is also likely that LCN2 is involved in the transition." (PMID 38645429, 2024). "Consistently, there is a significantly higher expression of serum LCN2 in patients with endometriosis compared to the control group." (PMID 38645429, 2024). "Lastly, growth and angiogenic factors like Angiopoietin 1 (ANG-1), Angiostatin, Lipocalin-2, and ErbB3 were decreased in endometriosis patients, while IGF-1 was significantly elevated in diseased patients." (PMID 31333337, 2019). "Furthermore, a behavioral study showed that induced endometriosis in mice led to increased depression and is also reflected in the induction of the expression of various targets in the brain, including the induction of the LCN2 protein and mRNA in the amygdala in females with endometriosis." (PMID 38645429, 2024). "The levels of angiogenin, CD105, ICAM-1, CXCL10, leptin, lipocalin-2, MMP-9, osteopontin, RBP4, PAI-1, ABP, CD31, TIM-2, and VCAM-1 were higher in the endometriosis group than in the control group." (PMID 34072419, 2021).
hypertriglyceridemia (5 papers, 2008 to 2025). A laboratory test result indicating elevated triglyceride concentration in the blood. "The blood level of lipocalin-2 associates with adiposity and hypertriglyceridemia." (PMID 32899610, 2020).
leishmaniasis (5 papers, 2021 to 2025). Infectious disease that is transmitted through the bite of hematophagous female phlebotomine sand flies. "Through PPI network analysis, hub genes such as Lcn2, Ltf, Mpo, Dnaja1, Hspa1a, Hspa1b and Hsph1 were screened out and might play important roles in the process of undernutrition promoting leishmaniasis." (PMID 38185681, 2024).